MYC (MYC proto-oncogene, bHLH transcription factor)
Diseases named in the same sentence as MYC in open-access papers (continued):
Sharing a sentence is not in itself a finding about the gene and the disease.
acute myeloid leukemia (continued). "As a splicing factor, RBM25 contributes to regulating MYC activity in acute myeloid leukemia." (PMID 34650978, 2021). "The exposure of acute myeloid leukemia (AML) cells to BIM-2 resulted in a remarkable antitumor activity as a consequence of the drug-mediated down-regulation of both MYC and BCL2, two oncogenes the over-expression of which is associated with the development of AML." (PMID 34073075, 2021). "In addition, the small molecule c-MYC inhibitor 10058-F4 inhibited proliferation and induced apoptosis through the mitochondrial pathway of apoptosis in several acute myelocytic leukemia cell lines." (PMID 26472107, 2015). "A possible relation to tumor development was shown in breast cancer, where a 17q23 amplification was related to increased expression of genes at that locus and in acute myeloid leukemia (AML), where amplification of 8p24 was associated with increased expression of genes such as MYC." (PMID 18221515, 2008). "In acute myeloid leukemia (AML), YBX1 serves as a disease-sustaining mediator of jak2-mutated myeloproliferative neoplasms, enhancing the translational capacity of oncogenic transcripts (including MYC) by recruiting polysome chains, thereby driving the survival and proliferation of AML cells." (PMID 40799245, 2025). "In addition, EPC1 is associated with acute myeloid leukemia (AML), where it may maintain its carcinogenic potential by inhibiting MYC accumulation and the apoptosis of AML cells." (PMID 40241795, 2025). "IGF2BP2, an m6A binding protein that enhances the stability and translation of mRNA, is highly expressed in acute myeloid leukemia AML cells and promotes leukemia progression by regulating the expression of MYC." (PMID 40830264, 2025). "For example, methyltransferases METTL3 and METTL14 enhance translation efficiency by adding m6A marks to MYC, a process that supports rapid proliferation in acute myeloid leukemia (AML)." (PMID 41446042, 2025). "The RNA demethylase FTO has been proposed to promote acute myeloid leukemia (AML) by demethylating N6-methyladenosine (m6A) from oncogenic transcripts, especially MYC." (PMID 41279954, 2025). "Besides, it has been shown that STAT3 regulates the transcriptional activity of MYC gene in primitive acute myeloid leukemia cells, invoking the possibility that NCAPG2 might interact with STAT3 and subsequently activate c-MYC expression." (PMID 38166947, 2024). "GNE-272 was able to modulate CBP/p300 MYC expression and showed antitumor potential in MYC-dependent acute myeloid leukemia (AML)." (PMID 39407454, 2024). "EPC1 and EPC2 are also related to acute myeloid leukemia (AML), which can directly or indirectly suppress the accumulation of MYC and apoptosis of AML cells, thereby maintaining oncogenic potential." (PMID 38439957, 2024). "Hence, this technology might be useful to reactivate potential tumor suppressor genes like BASP1, whose promoter is silenced by methylation in MYC-dependent acute myeloid leukemia." (PMID 36969025, 2023). "Thus, MYC is critical for balanced hematopoiesis and is frequently overexpressed in acute myeloid leukemia, likely by oncogenic Wnt/β-catenin signaling through the specific WRE associated with the MYC promoter (MYC 5′ WRE), leading to proliferation and terminal differentiation impairment of HSCs." (PMID 37568748, 2023). "Studies have shown that STAT3 regulates MYC expression in acute myeloid leukemia (AML), thereby controlling SLC1A5 transcription and OXPHOS and promoting the survival of leukemia stem cells." (PMID 36902385, 2023).
acute myeloid leukemia (continued). "dBET1 represents a proteolysis-targeting chimera (PROTAC) targeted against BET family members, and targeted BRD4 degradation in acute myeloid leukemia (AML) by dBET1 specifically impairs MYC transcription." (PMID 36969025, 2023). "Similarly, MYC is overexpressed in acute myeloid leukemia (AML) and chronic lymphocytic leukemia (CLL) and is able to inhibit the expression of the circadian clock gene Period2 (Per2), which is highly expressed in neutrophils where it enhances antitumor proliferation." (PMID 36966168, 2023). "Targeting TBK1 pharmacologically or by mRNA knockdown induces apoptosis and reduces cell viability in a subset of acute myeloid leukemia (AML) cells with an activated MYC signaling pathway necessary for survival." (PMID 36523963, 2022). "METTL3 upregulation increases translation of MYC, BCL2 and PTEN mRNAs in acute myeloid leukemia (AML), and METTL3 loss leads to increased levels of phosphorylated AKT, promoting differentiation of hematopoietic stem/progenitor cells (HSPCs)." (PMID 33922187, 2021). "Particularly, it was revealed that Galectin 3 expressed by MSCs in the TME of acute myeloid leukemia (AML) activates MYC expression and contributes to the cell adhesion between MSC and AML tumor, thereby promoting the survival of cancer cells." (PMID 34789315, 2021). "The ATPase subunit BRG1 has been shown to bind BRD9 in acute myeloid leukemia (AML) cells and is essential in supporting enhancer-mediated MYC expression in this context." (PMID 31652979, 2019). "Increased expression of c-MYC is observed in both Acute Myeloid Leukemia (AML) and T- cell Acute Lymphoblastic Leukemia (T-ALL)." (PMID 26517351, 2015). "As a tumor suppressor, miR-516a-5p targets several genes, including histone cluster 3, H2a, circ MYC proto-oncogene, BHLH transcription factor, and PBX homeobox 3 in non-small cell lung cancer, acute myeloid leukemia, and HCC." (PMID 40996984, 2025). "In our previous studies, we demonstrated that isoflavonoid 8-hydroxydaidzein induced apoptosis by downregulating acute myeloid leukemia (AML)-associated genes such as RUNX1, CCND2, and MYC in U937 cells while upregulating CDKN1A (p21) and suppressing BCL2 expression in K562 cells." (PMID 40508126, 2025). "In this context, YBX1 forms ribonucleoprotein complexes with IGF2BPs on m6A -modified transcripts, stabilizing key oncogenic mRNAs such as MYC and BCL2 in acute myeloid leukemia (AML)." (PMID 41346602, 2025). "Apart from FLT3, there are some other recurrent genetic alterations that are also found in other acute myeloid leukemia subtypes, including WT1 (14%), NRAS (10%), KRAS (4%) and MYC amplification (12%)." (PMID 38921185, 2024). "IGF2BP2 recruits proteins such as eIF4E and eIF3A to MYC, GPT2, and SLC1A5 mRNA, regulating glutamine metabolism in acute myeloid leukemia and modulating the immune response of macrophages through epigenetic reprogramming." (PMID 39726589, 2024). "The expression of METTL3 has been shown to be increased in acute myeloid leukemia (AML) patients, suppressing cell differentiation and apoptosis, and promoting cell proliferation through increased translation of c-MYC, BCL2, and PTEN." (PMID 39457524, 2024). "MYC overexpression has been observed in the majority of acute myeloid leukemia (AML) patients." (PMID 38383388, 2024). "For instance, super-enhancers inside the MYC locus are connected to BRD4 in several malignancies, including acute myeloid leukemia (AML) and multiple myeloma." (PMID 37509171, 2023).
acute myeloid leukemia (continued). "It was reported that METTL14 overexpression in acute myeloid leukemia is negatively regulated by SPI1 and mediates downstream targets, MYB and MYC, to accelerate acute myeloid leukemia (AML) oncogenesis." (PMID 34904301, 2022). "For example, in acute myeloid leukemia (AML), overexpressed METTL3 promotes cell proliferation and inhibits cell differentiation by modifying c-MYC, BCL-2, and PTEN with m6A." (PMID 36293529, 2022). "For example, the depletion of METTL3 in acute myeloid leukemia (AML) cells induced cell differentiation and apoptosis through METTL3-mediated m6A modification on MYC, BCL2 and PTEN mRNA, thus delaying AML progression." (PMID 34996469, 2022). "Previously, we reported that sustained degradation of BRD4 led to downregulation of CD44, MYC, and CXCR4 in acute myeloid leukemia (AML) stem cells and improved survival in a mouse model of AML." (PMID 35173274, 2022). "MYC was detected to influence the proliferation and differentiation of MSCs and to be involved in MSC-mediated drug resistance in acute myeloid leukemia." (PMID 35795041, 2022). "GAS6-AS1 is overexpressed in acute myeloid leukemia (AML) and promotes the progression of AML through the YBX1/MYC axis." (PMID 35962353, 2022). "Together, these data highlight both transcriptional and post-transcriptional regulation of MYC/MYCN by BETi in EPN, as previously reported in acute myeloid leukemia." (PMID 33668642, 2021). "However, scientific interest in this transforming activity has been increasing since new MYC-targeting drugs showed clinical activity in acute myeloid leukemia (AML)." (PMID 33801599, 2021). "Preclinically, administration of lentivirus-mediated short hairpin RNA (shRNA) targeting GAS6-AS1 considerably suppresses acute myeloid leukemia cell propagation and disease progression, indicating the crucial roles of GAS6-AS1/YBX1/MYC axis in leukemia." (PMID 34753494, 2021). "In other hematological malignancies, tucidinostat inhibits MYC and BCL2 in acute myeloid leukemia, and tucidinostat also downregulates BCL2 in combination with doxorubicin in peripheral T-cell lymphoma." (PMID 33097085, 2020). "Since MYC and MAX co-occupy the LCL MTHFD2 promoter and given MYC’s role in MTHFD2 regulation in acute myelogenous leukemia, we investigated a potential role for MYC in EBV induction of MTHFD2 expression." (PMID 31257153, 2019). "The depletion of m6A methyltransferase METTL3 reduces the translation efficiency of genes with m6A modification, such as c-MYC, BCL2 and PTEN, and promotes cell differentiation in acute myeloid leukemia." (PMID 30212448, 2018). "USP22 can deubiquitinate Sirt1 and enhance its stability through c-MYC-related network, leading to FLT3 tyrosine kinase inhibitors (TKIs) resistance in acute myeloid leukemia (AML)." (PMID 28567015, 2017). "For the first time, Weng and coworkers described the signaling axis SPI1-METTL14-MYB/MYC in normal myelopoiesis and leukemogenesis and proposed that METTL14 could be a new therapeutic target to treat acute myeloid leukemia (AML)." (PMID 40940799, 2025). "However, METTL14 is elevated in acute myeloid leukemia by regulating its mRNA targets through m6A modification, including MYB, MYC, and SPL1." (PMID 39457524, 2024). "Besides DLBCL, other tumor types showed an association of MYC and/or OxPhos gene signatures with increased resistance to various therapies, including ibrutinib in mantle cell lymphoma, neoadjuvant therapy in triple‐negative breast cancer, and venetoclax in acute myeloid leukemia." (PMID 37158102, 2023). "For example, near the 3′-end of the MYC locus, SEs are locally amplified at distinct locations in cervical cancer, acute myeloid leukemia (AML), lung adenocarcinoma (LUAD), and acute lymphoblastic leukemia, and thus likely controlling MYC gene expression via germline-specific chromosomal looping." (PMID 37501079, 2023).
acute myeloid leukemia (continued). "For example, the m6A methyltransferases METTL3/14 and WTAP could act as oncogenic factors by promoting the translation of several oncogenes including c-MYC, BCL2, PTEN, and mTOR in acute myeloid leukemia." (PMID 33584787, 2020). "Additionally, JQ1 treatment of the primary human fibroblast line LG1 and the acute myeloid leukemia cell line NOMO-1, the cell lines used to originally characterize the effect of JQ1 on MYC expression, led to decreased levels of POLRMT mRNA." (PMID 27590350, 2016). "Chromosomal translocations in some acute myeloid leukemia (AML) cases produce a fusion gene known as ZMYND11-MBTD1 (ZM), which recruits TIP60/KAT5 to stemness-related gene regions, including MYC, HoxA, Meis1, and Sox4." (PMID 41227365, 2025). "IGF2BP also stabilizes MYC, GPT2, and SLC1A5 mRNA to promote acute myeloid leukemia (AML) development." (PMID 41041073, 2025). "For instance, in acute myeloid leukemia (AML), increased m6 A levels on SP1, MYB, MYC, BCL2, and PTEN enhance the stability and translation of their corresponding mRNAs, contributing to the onset and progression of AML." (PMID 40382536, 2025). "In acute myeloid leukemia (AML), IMP2 stabilizes key mRNAs, including MYC, GPT2, and SLC1A5, that are essential for glutamine uptake and metabolism, fueling the TCA cycle and supporting AML cell proliferation and survival." (PMID 40141058, 2025). "In acute myeloid leukemia (AML), METTL3 promotes leukemogenesis and inhibits myeloid differentiation, potentially through the targeting of oncogenic genes such as MYC and CEBPA." (PMID 38012755, 2023). "By encouraging the translation of these mRNAs, METTL3 activity boosts and augments MYC, BCL2, and PTEN in human acute myeloid leukemia (AML)." (PMID 36551330, 2022). "Studies have reported its high expression in acute myeloid leukemia (AML), promoting cellular transformation and proliferation by the post-transcriptional regulation of ASB2, RARA, MYC, and CEBPA." (PMID 36371254, 2022). "In acute myeloid leukemia (AML), METTL14 regulates MYB and MYC via M6A modification, and plays a carcinogenic role in regulating cell self-renewal and inhibiting bone marrow differentiation." (PMID 35552266, 2022). "In acute myeloid leukemia (AML), both METTL3 and METTL14 can directly target MYC to enhance its translation efficacy and inhibit differentiation and increase proliferation." (PMID 34315512, 2021). "In acute myeloid leukemia (AML), abnormal expression of m6A regulatory factors, including METL3, METTL14, FTO, ALKBH5, and IGF2BP1/2/3, can regulate the expression of MYC." (PMID 33926508, 2021). "For instance, the METTL3 and METTL14, highly expressed in acute myeloid leukemia (AML), play a critical role in leukemia progression through promoting translation of target mRNAs, including MYB, MYC, BCL2, and PTEN." (PMID 33292652, 2020). "For example, in acute myeloid leukemia (AML), MSI2 expression has been shown to be an adverse prognostic marker that maintains the self-renewal program in AML by interacting with HOXA9, MYC, and IKZF2 mRNAs." (PMID 32448269, 2020). "Additionally, ABBV-075 downregulates MYC, CDK6, and BCLxL expression, upregulates p21 and BIM expression, and induces apoptosis in acute myeloid leukemia (AML) cells." (PMID 38539460, 2024). "It has been extensively reported that c-MYC, a well characterized oncogene involved in the induction of cell proliferation and growth, is targeted by METTL3 in numerous malignancies, including acute myeloid leukemia (AML)." (PMID 34530916, 2021).
acute myeloid leukemia (continued). "Moreover, in acute myeloid leukemia (AML) cells, METTL3 was abundantly expressed and promoted MYC, BCL2, and PTEN translation through m6A modification, which inhibited cell differentiation and fueled leukemia progression." (PMID 30518868, 2018). "This scenario parallels the mechanism of the antiproliferative role of DYRK1A in acute myeloid leukemia (AML) cells, where DYRK1A overexpression accelerates c-MYC degradation without affecting mRNA levels." (PMID 39482615, 2024). "Since MYC is a central oncogene inducing leukemic transformation in T cell acute lymphoid leukemia (T-ALL) and acute myeloid leukemia (AML), influencing AKT, ERK1/2 and MYC signaling may enhance the efficacy of chemotherapy in ALL and AML." (PMID 30651113, 2019). "In addition, METTL3 depletion in HSCs did not affect apoptosis, whereas knocking down of METTL14 induced acute myeloid leukemia (AML) cell apoptosis and promoted myeloid differentiation of normal HSCs via the SPI1–METTL14–MYB/MYC signaling axis." (PMID 35935968, 2022).